MICA (MHC class I polypeptide-related sequence A)
Diseases named in the same sentence as MICA in open-access papers (continued):
Sharing a sentence is not in itself a finding about the gene and the disease.
tumor (continued). "Correlation analysis indicated positive associations of CD160 ligands such as TNFRSF14 and HLA-C, and NKG2D (KLRK1) ligands MICA and MICB with the tumour-infiltrating CD56bright NK and CD8+ TEM cells." (PMID 39877370, 2024). "To further elucidate the intricate interplay between MICA+ HCC cells and MMP9+ macrophages, we conducted a meticulous analysis of scRNA-seq data derived from tumor samples." (PMID 38254761, 2024). "Novel strategies with bi-specific immunoconjugate constructs are focused on simultaneous targeting of NKG2D ligands, like MICA or ULBP1/2, and tumor-expressed antigens such as BCMA, CD19, and VEGFR2." (PMID 39339180, 2024). "The increase in expression of MICA and MICB led to an increase in NK cell-mediated cytotoxicity, leading to tumor growth suppression." (PMID 39161385, 2024). "The interaction between MICA and NKG2D triggers the cytotoxic activity of these immune cells, enhancing their ability to target and destroy tumor cells." (PMID 39335190, 2024). "Results: we presented a single-cell atlas of advanced HCC, highlighting the expression patterns of MICA and MMP9 in tumor cells and macrophages, respectively." (PMID 38254761, 2024). "Although NKG2D ligands significantly vary within species, the fact that the human ligand MICA is recognized by mouse NKG2D and activates mouse NK cells allows us to evaluate our strategy in tumor mouse models." (PMID 38180524, 2024). "Among these ligands, MICA and MICB are well characterized, with MICA more abundantly expressed in tumor cells." (PMID 39335190, 2024). "A combination of anti‐MICA/B and anti‐NKG2A antibodies showed a synergistic effect on immune‐mediated anti‐tumor response in this spheroid model." (PMID 38962943, 2024). "For example, combining the DNTM1/DNMT3a inhibitor hydralazine with VPA increased the expression of MICA and MICB ligands on NK cells and induced NK cell cytotoxicity against tumor cells." (PMID 38915093, 2024). "Research has demonstrated that radiotherapy at a dose of 20 Gy can increase the expression of MICA/B and ULBP1/2 on the surface of tumor cells, and, co-culture with these tumor cells can enhance the cytotoxicity of NK cells." (PMID 38162672, 2023). "This indicates that miR-20a downregulates MICA expression, reduces NK cell cytotoxicity, and is NKG2D-dependent in cancer cells to promote tumour growth." (PMID 37784183, 2023). "prepared an antibody targeting the shear site of MICA/B to protect it from being cleaved, allowing NK cells and CD8+ T cells to play their normal roles and kill tumor cells." (PMID 37426678, 2023). "We found the mRNA expression level of MICA, MICB, ULBP1, ULBP2, ULBP4, and ULBP5 was significantly higher in tumor tissues than that in adjacent normal tissues, whereas ULBP3 expression was lower in tumor tissues compared to adjacent normal tissues." (PMID 36210637, 2023). "MICA is a stress-induced ligand of the NK cell activating receptor NKG2D, which is essential for NK cells to kill virus-infected cells and tumour cells." (PMID 37784183, 2023). "The levels of the total ligands MICA, ULBP1, and HLAE were increased in more advanced tumor patients." (PMID 36931723, 2023). "NK cells recognise MICA on the tumour cell surface through NKG2D and promote a cytotoxic response leading to tumour cell elimination." (PMID 37784183, 2023). "Specifically, for Vδ1+ cells, NKG2D has been described to be involved in tumour recognition, which is dependent on tumour cell expression of NKG2D ligands MICA/B and ULBPs36–38." (PMID 36631610, 2023). "In C2GNT1-expressing tumor cells, GAL-3 was demonstrated to bind to core two O-glycans present in major histocompatibility complex class I-related chain A (MICA), which impeded ligand binding to NKG2D and subsequent NK cell activation and tumor destruction." (PMID 37898403, 2023).
tumor (continued). "Tumor-derived EVs also express the surface ligands of NKG2D, such as ULBP-2 and MICA/MICB, acting as negative regulators of NKG2D on NK cells in a dose-dependent manner and impairing cytotoxicity against tumor cells." (PMID 37175226, 2023). "Hyperthermia also increases the surface expression of MICA and MHC-I on tumor cells, making tumor cells more sensitive to lysis by NK cells and CD8+ T cells." (PMID 37251920, 2023). "First, we observed that MICA and ULBP5 were significantly higher in HCC tumor tissues than those in paired normal tissues, while ULBP3 was lower in tumor tissues compared to normal tissues in the OEP000321 dataset and Guilin cohort." (PMID 36210637, 2023). "This is highlighted by a recent study, showing that inhibition of MICA/MICB shedding and thus release of soluble ligands from the cell surface, prevented tumor growth in immunocompetent mouse models and reduced melanoma metastasis in a humanized model." (PMID 37143070, 2023). "UL16-binding protein (ULBP), MHC class I-related chain A (MICA) and B (MICB) are NKG2D ligands, commonly overexpressed on tumor cells." (PMID 37090711, 2023). "Major histocompatibility complex class I related chain A (MICA) is an important and stress-induced ligand of the natural killer group 2 member D receptor (NKG2D) that is expressed in various tumour cells." (PMID 37784183, 2023). "Although we found MICA positively correlated with anti-tumor immune cell infiltration in HCC, there were different results about the correlation of NKG2D ligands with tumor aggressiveness and the clinical prognosis in different cancer types and individuals." (PMID 36765808, 2023). "Mechanism studies revealed that BCL11B prevents cancer immune evasion by acting as a competitive endogenous RNA to upregulate MICA and MICB, which essentially control tumor immune surveillance." (PMID 35621244, 2023). "CD155 and MICA/MICB values oscillated up and down, while HLA-E intensity remained unchanged in infected OvCa tumor digests." (PMID 37949944, 2023). "The bispecific antibody cG7-MICA targets both the natural killer (NK) cell receptor NK group 2, member D (NKG2D) ligand MHC class I-related chain A (MICA), and CD24, which reduces tumor volume and improves survival rates in Huh-7-bearing nude mice." (PMID 37894750, 2023). "MICA is a stress-induced ligand of the NKG2D receptor that stimulates NK and T cell responses and was identified as a key determinant of anti-tumor immunity." (PMID 38035108, 2023). "MICA and MICB are homologous proteins of MHC class I molecules and are frequently and abundantly expressed on the surface of tumor cells and are reported to bind to the NK cell receptor NKG2D." (PMID 37508520, 2023). "MHC class I chain related A (MICA) is a ligand for NKG2D, which is expressed on many human tumor cells." (PMID 37253929, 2023). "Shedding MICA/B on tumor cell surfaces and subsequent soluble MICA/B can downregulate NKG2D expression on NK cells, which promotes tumor immune escape by impairing NK cell antitumor activity." (PMID 37628724, 2023). "The shed ligands MICA and MICB from the tumor cells directly pair with the NKG2D, leading to NK cell desensitization." (PMID 38041084, 2023). "NKG2D, a key receptor on NK cells, can recognize different ligands on tumor cells, including MHC class I polypeptide-related sequence A (MICA), to exert an antitumor effect." (PMID 36119072, 2022). "The tumor cell lines all variably express the DNAM-1 ligands CD112 and CD155, low levels B7-H6 (NKp30 ligand), while the NKG2D ligands MICA/B were expressed by HCT-15, HCT116, OVCAR-3, T-4D7, WM9, and DU145." (PMID 35119498, 2022). "It has been shown that tumour cells and CAFs escape immune cell attack by expressing high levels of PD‐L1 and PD‐L2, and shedding NKG2D ligands (MICA, MICB and ULBP1‐6) from the cell surface through proteolytic cleavage." (PMID 35731974, 2022).
tumor (continued). "Similar to Vδ2+ γδ T cells, the NKG2D-expressing Vδ1+ γδ T cells can be activated by stress-inducible MICA/MICB and ULBP1–6 family proteins, which are frequently upregulated in tumor cells." (PMID 35880177, 2022). "Another recent study evaluated MICA expression in 192 tumor, and adjacent normal tissue samples from 96 CRC patients revealed that MICA expression was significantly higher in CRC tumors than the adjacent normal tissue." (PMID 35346234, 2022). "NKG2D is a lectin-like type 2 transmembrane receptor mostly expressed by human NK cells and binds to MHC-related ligands such as ULBPs, MICA, and MICB, which are highly expressed in tumor cells but rarely in healthy cells." (PMID 35880177, 2022). "NKG2D-expressing Vδ1+γδ T cells can be activated by stress-induced MHC class I chain-related antigens A and B (MICA/MICB) and UL16-binding proteins (ULBP16), which are upregulated in tumor cells contrary to healthy cells." (PMID 36499125, 2022). "Specifically, the dimerization of epidermal growth factor family members, HER2 and HER3, upregulated MICA and MICB expression via the PI3K axis, which increased NK cell recognition and killing of tumor cells." (PMID 35565467, 2022). "Due to cellular stress and DNA damage, MHC class I polypeptide-related sequence A (MICA) and MHC class I polypeptide-related sequence B (MICB) are expressed on the tumor cell surface, which can bind to NKG2D to induce an immune response." (PMID 36558902, 2022). "Studies have shown that MICA and MICB (stress-induced proteins as NKG2D ligands) are upregulated in hepatocytes from chronic liver diseases and tumor cells from HCC lesions." (PMID 36611926, 2022). "We discover that Entinostat, Decitabine, Ricolinostat and Vorinostat significantly increase MICA and MICB expression on tumour cells and CAFs." (PMID 35731974, 2022). "MICA is a ligand for activating the natural killer group 2, member D (NKG2D) receptor on the NK cells, and the shedding of MICA downregulates the NKG2D receptor, leading to tumour cell escape from T cells and NK cells." (PMID 35466515, 2022). "After exposure to cytotoxic treatment, neoplastic cells upregulate the expression of MICA and MICB, which increases the anti-tumor activity of γδ T cells." (PMID 36499125, 2022). "The study reported that after treatment with MICA α3 domain-specific antibodies there was an increase in the binding of NKG2D to target ligands, thus inducing greater tumor immunity mediated by NK cells." (PMID 35919494, 2022). "Similar to Vδ2 cells, Vδ1 cells also mediate tumor cell lysis through recognizing ULBP3 and MICA by NKG2D." (PMID 35747139, 2022). "Soluble MICA can downregulate the expression of the NKG2D activating receptor on NK and T cells, resulting in tumor evasion from the immune system." (PMID 33422072, 2021). "MICA and MICB (Rae1 in mouse) have a key role in the recognition of tumor cells by the innate immune system where their engagement with NKG2D receptors on NK cells triggers NK cell-mediated cytotoxicity." (PMID 33789714, 2021). "In this model, the contemporary targeting of NKG2D ligands MICA/B on tumor cells, and the inhibitory receptor NKG2A on NK cells, led to a synergistic effect in blocking tumor cell growth, even if it expressed the NKG2A ligand HLA-E." (PMID 34298630, 2021). "MICAB1, targeting MICA and MICB, promoted an efficient tumor target cell lysis by PBMCs when compared to the anti-EGF-R mAb cetuximab and the anti-CD20 mAb rituximab, which are widely used in clinical practice." (PMID 35967081, 2021). "Among them, blockade of proteolytic shedding of MICA or MICB through genetic engineering or via antibody-dependent metalloproteinase inhibition, restored potent NK cell-mediated killing tumor targets." (PMID 34201655, 2021). "NKG2DL, like the MHC class I chain-related protein A and B (MICA and MICB) or the UL 16 binding protein 1–6 (ULBP1–6), are highly expressed on the surface of stressed cells but also by tumor cells." (PMID 33800301, 2021).
tumor (continued). "The considerable CXCL1-induced up-regulation of TLR4, TNFSF10/TRAIL, and KITLG expression along with MICA/MHCI down-regulation, enable tumor evasion from immune surveillance." (PMID 34195201, 2021). "In LNT-229 glioma cells, it has been observed that an autocrine circuit that involves TGF-β and MMP production promotes shedding of MICA and ULBP-2 and negatively affects the expression of these NKG2DL on the tumor cell surface." (PMID 34394116, 2021). "Surface MICA is a ligand for the activating receptor natural killer group 2 member D (NKG2D) on NK cells; however, soluble MICA can downregulate the expression of NKG2D on NK cells, which contributes to tumour immune evasion." (PMID 33923305, 2021). "We therefore developed a novel mAb directed against both MICA and MICB, named Mia4, which specifically stained the MICA and MICB proteins on formalin-fixed, paraffin-embedded tumor tissue sections." (PMID 35967081, 2021). "NKG2DLs, including MICA/B and ULBP1/2/3, are commonly expressed in tumor cells and their main role is to give effect to NK cells to eliminate tumors." (PMID 34084160, 2021). "NKG2D ligands (MICA, MICB, and ULBP1‐6) are expressed on stressed or tumor cells, favoring their destruction." (PMID 34323406, 2021). "By engaging NKG2D and overriding the inhibitory signals of killer inhibitory receptors (KIRs) and/or CD94/NKG2A/B, MICA effectively activates NK, γδ T cells and αβ CD8+ T cells to kill virus-infected cells or tumor cells." (PMID 34208618, 2021). "In this review, we revised data that position MICA and MICB as attractive targets in I-O to leverage NKG2D-dependent NK cell-mediated anti-tumor effects and catalyze tumor immunity." (PMID 34394116, 2021). "Activating receptor NKG2D on the surface of NK cells and stressing-inducing ligand MICA and MICB on tumor cells can all be induced by HDAC inhibitors to increase NK cell killing of tumor cells." (PMID 34579759, 2021). "Consistent with our findings in oral tumor cells, we observed higher levels of NK cell-mediated ADCC against anti-MICA/B mAb-treated pancreatic PL12 cells when compared to MP2 tumors." (PMID 33440654, 2021). "MICA is a ligand to natural killer group 2D (NKG2D), an activating receptor that is important for the anti-tumor immune response." (PMID 33868281, 2021). "HDAC inhibitors reduced tumor growth by downregulating c-Myc in a CRBN-independent manner, while upregulating MICA expression and, thus, enhancing the efficacy of immunotherapy." (PMID 33757580, 2021). "Like natural killer cells, γδ T cells also express the NKG2D receptor that induces cytolysis upon binding to the stress-inducible proteins such as MHC class I chain-related molecules (MICA, MICB), and UL16-binding proteins (ULBPs) on tumor or stressed cells." (PMID 34117317, 2021). "A recent study aimed at increasing NK cell activity against cancer cells utilized antibodies against the proteolytic shedding domains of MICA and MICB (the tumor ligands for NKG2D), which are often shed by the TME to inhibit NK cell function." (PMID 32153582, 2020). "In our previous study, we showed that a fusion protein composed of the MICA extracellular domain (MICA-ECD) and an anti-CD20 single-chain antibody (ScFv) induced NK cell-mediated killing of CD20+ tumor cells." (PMID 32010486, 2020). "MICA is a ligand for natural killer (NK) group 2 member D (NKG2D) and is expressed on tumor cells to elicit attack by NK cells." (PMID 32245188, 2020). "TGF-β appears to act simultaneously on NK cells and tumor cells via miR-183, with the result to inhibit the NK cells' anti-tumor activity by down-regulating DAP12, in NK cells, and NKG2D ligands (MICA and MICB), in cancer cells." (PMID 32161594, 2020). "As an essential receptor for the activation of NK cells, NKG2D is blocked by many ligands (e.g., MICA, MICB, and ULBP1–6) upregulated in tumor cells as a result of abnormal cellular stress in the TME." (PMID 32762681, 2020).
tumor (continued). "A recent study demonstrated that antibodies targeting MICA and MICB can prevent NK cell recognition and tumor cell binding, inhibiting tumor growth in fully immunocompetent mouse models as well as humanized mouse models." (PMID 32762681, 2020). "Histone deacetylase inhibitors such as sodium valproate enhance NK-mediated cell killing by increasing expression of NKG2D ligands MHC class I chain-related molecules MICA and MICB on tumor cells." (PMID 33287875, 2020). "Alternative tumor immune escape mechanisms include upregulation of HLA-E on the tumor cell surface and release of soluble NKG2D ligands, such as MICA and MICB." (PMID 32903482, 2020). "Similar to how tumour cells escape from T cell-mediated lysis, some tumour cells can downregulate NKG2D ligands such as MICA/B and ULBPs, to avoid recognition by NK cells." (PMID 33207697, 2020). "Some tumors have the capacity to shed NKG2D ligands, such as MHC class I polypeptide-related sequence A (MICA) and MICB by metalloproteinase-mediated cleavage, resulting in reduced ligand on the surface of tumor cells." (PMID 32244723, 2020). "Initially, we confirmed that the axis is functional in NK targeting of our cell lines by NK cell functional assays in the presence/absence of neutralising antibodies to NKG2D and the MICA and MICB tumour expressed ligands." (PMID 30908480, 2019). "For instance, AR42 and panobinostat provoke an upregulation of MHC class I/II and of MICA/MICB on tumor cells, an increase in tumor infiltration by T cells and a decrease in the number of immunosuppressive MDSC." (PMID 31805711, 2019). "GEM-treated tumour cells were found to express increased amounts of the NKG2D ligands ULBP2 and MICA/B at their surface and microarray analysis suggested this was due to increased transcription induced by GEM treatment." (PMID 30733494, 2019). "We observed increased spheroid alteration, tumor cells apoptosis and spheroid infiltration when anti-NKG2A was added to anti-MICA/B, compared to anti-MICA/B alone or isotype controls." (PMID 30871626, 2019). "The expression of surface MICA and MICB was markedly reduced for each epithelial cancer cell line when cloaked with tumour cells." (PMID 30908480, 2019). "More recently, Ab-based inhibition of MICA and MICB shedding promoted anti-tumour immunity through the activation of NK cells through dual stimulation of the NKG2D and CD16 Fc receptor pathways." (PMID 30626155, 2019). "In melanoma patients MMPs released by CAFs support NK cell immunosuppression by selectively cleaving MICA and MICB on tumor cells." (PMID 30939820, 2019). "Hence, the nature of the microenvironment within and surrounding tumors may have the potential of altering the impact of NKG2D activation, and this aspect deserves attention while studying the impact of NKG2D interaction with MICA and other such ligands on the tumor cell surface." (PMID 31009335, 2019). "As a consequence, MICA and MICB are upregulated, which improves tumor cell recognition by innate immune effectors and thus the sensitivity to natural killer cell-mediated killing." (PMID 31805711, 2019). "Exosome-delivered MICA and ULBP can reduce the cell-killing function of T-cells by inhibiting NKG2D signaling pathway, leading to tumor immune escape." (PMID 31181729, 2019). "Soluble MHC class I-related chain A (MICA), an inhibitory NKG2D ligand, secreted by tumor cells, binds to NK cells, thus impairing their ability to activate DCs." (PMID 31627733, 2019). "In the liver, hypoxia-derived HIF-1α induces changes in surface and soluble MHC class I polypeptide-related sequence A (MICA), thus impairing NK cell’s ability to recognize the tumor." (PMID 31450598, 2019). "MICA/B expression by tumor cells and NKG2D pathway engagement prompted us to test the antitumor potential of an ADCC-enhanced anti-MICA/B antibody." (PMID 30871626, 2019).